SPTB (spectrin beta, erythrocytic)
Description:
Spectrin is the major constituent of the cytoskeletal network underlying the erythrocyte plasma membrane. It associates with band 4.1 and actin to form the cytoskeletal superstructure of the erythrocyte plasma membrane.
Synonyms: EL3; HS2; HSPTB1; SPH2
Tractability: Antibody: its Gene Ontology location is reachable by antibodies, with medium confidence. PROTAC: ubiquitination databases record sites on it; its protein half-life has been measured.
Gene: Protein-coding gene on chromosome 14 (64,746,283 to 64,879,907, reverse strand). Ensembl gene ENSG00000070182.
Subcellular location: Cytoplasm, cytoskeleton; Cytoplasm, cell cortex
Subcellular location (Human Protein Atlas): Cytosol
Pathways (Reactome):
Developmental Biology: Interaction between L1 and Ankyrins; NCAM signaling for neurite out-growth
Signal Transduction: RAF/MAP kinase cascade
Vesicle-mediated transport: COPI-mediated anterograde transport
Gene Ontology:
Molecular function: actin filament binding; ankyrin binding; protein binding; actin binding; structural constituent of cytoskeleton
Biological process: modification of postsynaptic actin cytoskeleton; actin cytoskeleton organization; regulation of cell shape; synapse organization
Cellular component: glutamatergic synapse; protein-containing complex; spectrin; spectrin-associated cytoskeleton; actin cytoskeleton; cell junction; cortical actin cytoskeleton; cytoplasmic side of plasma membrane; cytosol; plasma membrane; cell cortex; cytoskeleton; postsynapse; synapse
Genetic constraint (gnomAD): Loss-of-function variants: 47 observed, 263.22 expected, observed/expected ratio (o/e) 0.18, 90% interval 0.14 to 0.23. The upper end of that interval is the gene's LOEUF score, 0.23, which puts it in group 1 of 6, group 1 being the genes least tolerant of losing a copy. Missense variants: 2,715 observed, 3,137.9 expected, observed/expected ratio (o/e) 0.87, 90% interval 0.84 to 0.89. Synonymous variants: 1,231 observed, 1,288.5 expected, observed/expected ratio (o/e) 0.96, 90% interval 0.91 to 1.
Homologues: Orthologues: macaque SPTB (98% identical), chimpanzee SPTB (95% identical), dog SPTB (92% identical), mouse Sptb (91% identical), rat Sptb (91% identical), pig SPTB (90% identical), rabbit SPTB (90% identical), guinea pig SPTB (88% identical), zebrafish sptb (63% identical), tropical clawed frog sptb (61% identical), Caenorhabditis elegans unc-70 (45% identical). Paralogues in human: SPTBN1 (60% identical), SPTBN2 (53% identical), SPTBN4 (47% identical), SPTBN5 (24% identical), DST (24% identical), MACF1 (23% identical), SYNE1 (23% identical), SYNE2 (22% identical), DMD (18% identical), UTRN (18% identical), PLEC (18% identical), SPTAN1 (17% identical), and 24 more.
Diseases named in the same sentence as SPTB in open-access papers:
SPTB is named in the same sentence as 101 diseases in open-access papers, as found by Europe PMC text mining. Sharing a sentence is not in itself a finding about the gene and the disease. The quoted sentences say what the papers report.
hereditary spherocytosis (21 papers, 2019 to 2025). Hereditary spherocytosis is a congenital hemolytic anemia with a wide clinical spectrum (from symptom-free carriers to severe hemolysis) characterized by anemia, variable jaundice, splenomegaly and cholelithiasis. "Reverse phenotyping by pediatric hematology confirmed the diagnosis of hereditary spherocytosis type 2 related to the SPTB variant, while the pathogenic variant in USP9X explained the ID/DD phenotype and most of the dysmorphic features." (PMID 38560291, 2024). "The variants in the genes that are mainly responsible for the vertical membrane anchoring of the cytoskeleton (ANK1, EPB42, SLC4A1, SPTA1, and SPTB) are the cause of hereditary spherocytosis (HS)." (PMID 38069343, 2023). "The new missense mutation p.C183Y was identified using WES in the SPTB gene, which is most likely the cause of clinical symptoms typical of hereditary spherocytosis (membranopathy) due to structural and functional impairments of human β-spectrin." (PMID 34681667, 2021). "Mutations in ANK1 and SPTB have been linked to erythrocyte membrane disorders including hereditary spherocytosis, in which clinically significant iron overload is commonly seen." (PMID 32354332, 2020). "Multiple mutations in human SPTB disrupt the erythrocyte cytoskeleton and cause hereditary elliptocytosis or spherocytosis, which are characterized by elliptical and/or spherical erythrocytes." (PMID 33108368, 2020). "Interestingly, our patient also harbored a heterozygous SPTB gene variant (c.2555C > T; p.Thr852Met), which is associated with hereditary spherocytosis and elliptocytosis, though its clinical significance in this case remains uncertain." (PMID 41473418, 2025). "This case report found that SPTB gene mutations may cause liver dysfunction and cirrhosis in addition to hereditary spherocytosis, and this finding expands the phenotypic spectrum of SPTB." (PMID 35223921, 2022). "The frameshift p.Leu884GlyfsTer27 variant of ANK1, nonsense p.Trp652Ter variant of the SPTB, and missense p.Arg490Trp variant of PKLR were detected in all four hereditary spherocytosis cases." (PMID 36832257, 2023). "Remarkably, mutations in the SPTBgene (β-spectrin) were found in 34.6% of the patients with hereditary spherocytosis(HS), suggesting that SPTB is a major HS gene inthe Southeast of Brazil." (PMID 32266426, 2020). "Hereditary spherocytosis (HS) is an inherited disorder characterized by anemia, splenomegaly, and spherical-shaped erythrocytes, caused by mutations in erythrocyte membrane Protein Genes (ANK1, SPTB, SLC4A1, SPTA1, and EPB42)." (PMID 33014018, 2020).
anemia (13 papers, 2019 to 2026). A reduction in the number of red blood cells, the amount of hemoglobin, and/or the volume of packed red blood cells. "Patients with ANK1 gene mutations experienced more severe anemia compared to those with SPTB gene mutations (p = 0.041)." (PMID 41721551, 2026). "The SPTB c.6005G>A (p.Trp2002*) mutation was inherited from the mother, who exhibited mild anemia, jaundice, and splenomegaly." (PMID 41660043, 2026). "In our clinical study, we found a case of HS caused by a novel mutation in the SPTB gene: the 22-year-old female patient exhibited clinical symptoms including jaundice and anemia, with a family history of splenectomy due to anemia." (PMID 39959857, 2024). "Given the current body of evidence, it is still unclear which of these causal pathways links anemia to sPTB." (PMID 35356651, 2022). "Our genotype-phenotypic association study showed that ANK1-HS was more severe than SPTB-HS in anemia." (PMID 33868383, 2021). "This suggested that patients with ANK1 mutations had more severe anemia than those with SPTB mutations." (PMID 33868383, 2021). "Patients with ANK1 mutations had more severe anemia than those with SPTB mutations (significantly lower RBC, HB, MCHC, and HCT)." (PMID 33868383, 2021). "The results confirmed that the anemia degree of HS patients caused by ANK1 was more serious than that of patients with SPTB deficiency." (PMID 33868383, 2021). "The data we included suggest that children with ANK1 gene mutation have more severe anemia than those with SPTB gene mutation, which may lead to earlier treatment of children with ANK1 gene mutation and younger age of onset." (PMID 40909430, 2025). "The study found that children with ANK1-HS had significantly more severe anemia than those with SPTB-HS." (PMID 40909430, 2025). "After excluding potential influencing factors such as splenectomy, the anemia symptoms in ANK1-HS patients were more severe than those in SPTB-HS patients." (PMID 40909430, 2025). "This indicates that ANK1-HS patients have more severe anemia phenotype compared to SPTB-HS patients." (PMID 39044243, 2024). "The results confirmed that HS patients with ANK1 defects diagnosed in childhood experience more severe anemia compared to those with SPTB defects." (PMID 39044243, 2024). "This suggests that the anemia phenotype is more severe in pediatric ANK1-HS patients compared to pediatric SPTB-HS patients." (PMID 39044243, 2024). "ANK1-HS patients exhibited more severe anemia compared to cases with SPTB-HS, showing lower levels of RBC and HB (P < 0.05)." (PMID 39044243, 2024). "We report a case of severe anemia caused by complex hereditary spherocytosis (HS) and X-linked sideroblastic anemia (XLSA) with two mutations in the spectrin beta (SPTB) and 5-aminolevulinic acid synthase (ALAS2) genes." (PMID 36902777, 2023). "For example, the highest contributing risk factor to sPTB is maternal anemia, and the biological links between anemia and sPTB are also not yet fully understood." (PMID 35356651, 2022). "However, in patients under 14 years of age, ANK1-HS had more severe anemia compared to SPTB-HS, which may be related to the relatively small number of children in previous studies." (PMID 39044243, 2024). "Studies showing that anemia provided protection against sPTB were lacking." (PMID 32546709, 2020).
elliptocytosis (8 papers, 2019 to 2025). "Mutations in SPTB have been implicated in a spectrum of hereditary red blood cell disorders, including HS type 2, hereditary elliptocytosis, and neonatal hemolytic anemia." (PMID 39959857, 2024). "SPTB is involved in erythrocyte membrane stability, and the mutations in this gene have been implicated in spherocytosis type 2 and hereditary elliptocytosis." (PMID 35292026, 2022). "Spectrin beta, erythrocytic (SPTB) plays a role in the stability of erythrocyte membranes and is associated with spherocytosis type 2, hereditary elliptocytosis, and neonatal hemolytic anemia." (PMID 31195974, 2019). "Unlike ANK1 mutations, which were identified only in HS patients, SPTB mutations could result in other diseases including hereditary elliptocytosis and hereditary pyropoikilocytosis." (PMID 34335240, 2021).
Obesity (8 papers, 2019 to 2025). Accumulation of substantial excess body fat. "This study demonstrates that earlier gestational age and shorter cervical length at UIC, higher levels of preoperative serum inflammatory markers, and maternal prepregnancy obesity are associated with an increased risk of sPTB after UIC." (PMID 38138905, 2023). "In this model, earlier gestational age at operation, short cervical length, high preoperative ESR level, and obesity were independently associated with an increased risk of sPTB after UIC." (PMID 38138905, 2023). "The results of this study demonstrated that earlier gestational age, shorter cervical length at UIC, preoperative ESR, and maternal prepregnancy obesity were associated with sPTB after UIC." (PMID 38138905, 2023). "Higher levels of preoperative serum inflammatory markers and obesity significantly increased the risk of sPTB after UIC." (PMID 38138905, 2023). "This study, in concordance with others, underscores that underweight, overweight, and obesity independently elevate the risk of sPTB in twin pregnancies." (PMID 38129929, 2023). "While obesity can directly influence the circulating metabolome, if these changes are themselves important factors in sPTB risk, an exacerbation of these effects would be expected in the obese sPTB group." (PMID 33201881, 2020). "On the other hand, pro-inflammatory status related to obesity has also been associated with a higher risk for sPTB and preterm premature rupture of membranes." (PMID 32546709, 2020). "In general, underweight has been related to a higher risk of sPTB and obesity related to PROM and pi-PTB." (PMID 31511664, 2019). "Additionally, the presence of diabetes, particularly when combined with obesity, significantly elevated the risk of sPTB." (PMID 38999295, 2024). "Since sPTB is caused by various factors, and obesity has different effects on each, the effect of obesity should be analyzed in detail to elucidate any direct correlation with PTB or its effects during the gestational weeks of PTB rather than a general analysis." (PMID 38138905, 2023). "Univariate analysis discerned significant associations (P < 0.05) between sPTB and certain variables, including age ≥ 35 years, pre-pregnancy overweight, underweight and obesity, nulliparity, pre-pregnancy diabetes, pre-pregnancy hypertension, and cervical incompetence." (PMID 38129929, 2023). "Notably, body mass indices (BMIs) for obesity (>30 kg/m2) and underweight (<18.5 kg/m2) relative to the normal range increase risks of sPTB, and the association of BMI with inflammation also exhibits a “U-shaped” behavior." (PMID 33201881, 2020). "In fact, elevated fatty acid ethanolamides and reduced lysophosphatidylcholines with unchanged levels of phosphatidylcholines are the features observed in obesity, the same changes were found by us to be exacerbated in the obese sPTB group." (PMID 33201881, 2020). "A retrospective cohort study containing 34 primiparous participants with obesity showed that women with sPTB <31 wks gestation had a metabolomic profile containing higher concentrations of auto-oxidation metabolites and evidence of dyslipidemia compared to those delivering at term." (PMID 41019841, 2025). "Overweight and obesity were associated with a higher risk of pi-PTB, despite a lower risk of sPTB." (PMID 31511664, 2019).
preeclampsia (7 papers, 2015 to 2025). Preeclampsia is a hypertensive disorder of pregnancy that is characterized by new-onset hypertension with proteinuria presenting after 20 weeks of gestation, and depending on mild or severe forms may initially present with severe headache, visual disturbances, and hyperreflexia. "Our reviews indicated that three risk factors are related to sPTB, with significant overlap: low calcium intake, low vitamin D intake, and preeclampsia." (PMID 35356651, 2022). "We recently identified that genes that drive circadian rhythms in cells, termed molecular clock genes, are deregulated in maternal blood of women with spontaneous PTB (sPTB) and in the placenta of women with preeclampsia." (PMID 36712876, 2022). "There is evidence that biomarkers that predict preeclampsia may be similar to those that can predict sPTB, as sPTB is suggested to be part of the placental insufficiency spectrum, like preeclampsia." (PMID 40128623, 2025). "Finally, two genes differentially expressed in PTB clinical subtypes and classified as fast evolving in each of the three categories, NFIB (preeclampsia and LED) and CXCR4 (sPTB)." (PMID 26641094, 2015).
diabetes (5 papers, 2018 to 2025). "Methods/Results: The analysis revealed that cervical length at the time of operation, preoperative erythrocyte sedimentation rate levels, and diabetes were independent risk factors for sPTB." (PMID 38999295, 2024). "Other known risk factors for sPTB include maternal medical disorders like hypertension, asthma, diabetes and thyroid disease." (PMID 29954448, 2018). "Additionally, our study introduces a novel perspective by examining the impact of diabetes mellitus and chronic hypertension on sPTB risk in twin pregnancies, revealing these conditions as additional risk factors." (PMID 38129929, 2023). "Based on the LRT, fetal fraction significantly improved model fit (p < 0.05) for HDP, birthweight < p10, birthweight < p2.3, total sPTB, moderate to late sPTB and diabetes." (PMID 39358906, 2025). "The prevalence of adverse pregnancy outcomes was 5.7% for HDP, 10.2% for birthweight < p10, 3.2% for birthweight < p2.3, 3.4% for all sPTB, 3.4% for diabetes and 1.3% for congenital anomalies." (PMID 39358906, 2025). "Mothers with sPTB and iPTB were more likely to be older (aged ≥35 years), self-identify as Black or Asian, have a lower educational attainment, be overweight, have pregestational diabetes and hypertension, and have a history of PTB." (PMID 39535795, 2024). "Adding fetal fraction to the base model improved model fit for HDP, birthweight < p10, birthweight < p2.3, all sPTB, and diabetes, but not for congenital anomalies (LRT p < 0.05)." (PMID 39358906, 2025). "The results indicated that there were differences in age (P < 0.001), pre-pregnancy BMI (P < 0.001), nulliparity (P = 0.045), pre-pregnancy diabetes (P < 0.001), pre-pregnancy hypertension (P = 0.001), and cervical incompetence (P < 0.001), between women with and without sPTB." (PMID 38129929, 2023).
gestational diabetes (5 papers, 2016 to 2022). Carbohydrate intolerance first diagnosed during pregnancy. "After adjusting for other substance use and confounders, we found positive associations between prenatal cannabis use and LBW, PTB, SPTB, MPTB, VPTB, SGA, major congenital anomalies, caesarean section and gestational diabetes." (PMID 36417349, 2022). "Additionally, a meta-study showed that pregnant women with gestational diabetes mellitus (GDM) had a higher risk of sPTB than pregnant women without GDM." (PMID 36506912, 2022).
Hypertension (5 papers, 2016 to 2024). The presence of chronic increased pressure in the systemic arterial system. "Of these, 67 studies met the inclusion criteria, including 29 on SGA/LBW, 34 on hypertensive disorders of pregnancy, 11 on sPTB and 9 on GDM." (PMID 27754451, 2016).
urinary tract infection (4 papers, 2020 to 2024). "After adjusting for ethnicity and microbiota profile, urinary tract infection during pregnancy and vaginal blood loss in the 1st or 2nd trimester remained associated with sPTB (aOR 4.0, 95% CI 1.3–12.9, and aOR 3.2, 95% CI 1.2–8.7, respectively)." (PMID 38802950, 2024). "First or second trimester vaginal bleeding (aOR: 3.6, 95% CI: 1.4–9.0) and urinary tract infection during pregnancy (aOR: 4.9, 95% CI: 1.7–13.9) were associated with sPTB in multivariate analysis." (PMID 35620540, 2022). "The majority of women with sPTB fulfilled at least one criterion for the identification of maternal infection (65.9%), and more than half reported having urinary tract infection during pregnancy." (PMID 32215453, 2020). "Indeed, sPTB is also related to infections or inflammations outside the genital tract, such as periodontitis, urinary tract infections, and inflammatory bowel disease, indicating that spontaneous preterm birth may be closely related to gut inflammation." (PMID 37317145, 2023).
bacterial vaginosis (3 papers, 2020 to 2023). Infection caused by bacterial overgrowth in the vagina. "These opportunistic pathogens have demonstrated distinct associations with conditions like bacterial vaginosis (BV), aerobic vaginosis (AV), and sPTB, although their mere presence or absence is insufficient to explain causality." (PMID 38196946, 2023). "There is also consideration on how probiotics may mitigate the risk of sPTB and bacterial vaginosis." (PMID 38196946, 2023).
intra-amniotic infection (3 papers, 2015 to 2025). "Recent studies reported elevated β-defensin levels in amniotic fluid in sPTB-related conditions, including intra-amniotic infection, inflammation, PPROM, and cervical insufficiency." (PMID 40076749, 2025). "Therefore, this study aims to investigate BD2 expression in the amniotic membrane of patients with sPTB and chorioamnionitis." (PMID 40076749, 2025). "Our study demonstrates that BD2 plays a crucial role in regulating the inflammatory response and maintaining epithelial barrier integrity in infection/inflammation conditions during pregnancy, such as chorioamnionitis, ultimately contributing to the prevention of sPTB." (PMID 40076749, 2025).